TLR9 (toll like receptor 9)
Diseases named in the same sentence as TLR9 in open-access papers (continued):
Sharing a sentence is not in itself a finding about the gene and the disease.
breast cancer (continued). "In our previously published EA breast cancer cohort, ~ 90% of TNBC patients with high tumor TLR9 expression survived over 10 years." (PMID 28886076, 2017). "In the present study, M13SV1-EGFP-Neo human breast epithelial cells, MDA-MB-435-Hyg human breast cancer cells and two hybrids M13MDA435-1 and -3 were investigated for TLR4 and TLR9 expression and signaling." (PMID 27187369, 2016). "In accordance to recently published data MDA-MB-435-Hyg human breast cancer cells and M13MDA435-1 and -3 hybrid cells exhibited comparable expression levels of TLR4, TLR9, TRIF, Myd88, and TRAF6." (PMID 27187369, 2016). "However, similar to other reported TLR9-mediated effects of cell-derived self-DNA, complex formation of such cell-derived DNAs with the cationic antimicrobial peptide LL-37 enhanced DNA uptake into viable breast cancer cells, and was a requirement for the invasion-inducing effects." (PMID 25101078, 2014). "These hypoxia effects on TLR9 mRNA and protein expression were mediated via HIF-1α in breast cancer cells in vitro." (PMID 25101078, 2014). "Samples of mammary carcinomas with recurrence have also exhibited a significant increase in the mRNA levels of TLR3, TLR4, and TLR9." (PMID 22295250, 2012). "From these studies, we know that TLR9 and TLR2 play a key role in breast cancer proliferation and metastasis." (PMID 20618976, 2010). "Inherent defects in specifically the breast cancer CIC population PPRs TLR2 and TLR9 are likely to contribute to dysfunction in the initiation of the type I IFN response leading to a failure of feed-forward signal amplification via IRFs and STAT signaling." (PMID 21079774, 2010). "Not only TLR9 and TLR2, but also other TLRs are involved in the process of breast cancer development." (PMID 20618976, 2010). "Metabolic stress in the MDA-MB-231 breast cancer cell line promotes PINK1-dependent packaging of mtDNA into EVs that are released via the Rab27 pathway, and these EVs alter invasive behavior of other tumor cells by activating TLR9 signalling." (PMID 40488669, 2025). "Decreased TLR9 expression is associated with poor prognosis in triple negative breast cancer (TNBC), but the role of TLR9 in breast cancer pathophysiology is currently unclear." (PMID 39644451, 2024). "In addition, BBR suppresses the toll-like receptor 9 (TLR9)-myeloid differentiation factor 88 (MyD88)–nuclear factor kappa-B (NF-κB) pathway and partly reverses doxorubicin (Dox)-exacerbated breast cancer metastasis." (PMID 35153781, 2022). "Moreover, TLR4 and TLR9 as well as TRIF, Myd88 and TRAF6 expression levels of MDA-MB-435-Hyg breast cancer cells were comparable to M13MDA435-1 and -3 hybrid cells." (PMID 27187369, 2016). "Synthetic TLR9 agonists, CpG–ODNs have demonstrated promising direct and immune system-mediated anti-cancer effects against breast cancer in pre-clinical models but they have not been studied in clinical breast cancer trials." (PMID 25101078, 2014). "Although breast cancer is not currently considered to have viral etiology, various viruses known to be capable of down-regulating TLR9 expression have also been detected in breast cancers." (PMID 25101078, 2014). "According to our preliminary data, such patients with low TLR9-TNBC and poor prognoses may represent up to 10% of all breast cancer patients." (PMID 24273604, 2013). "Daily treatment of mice with intraperitoneal (i.p.)chloroquine (80 mg/kg/day) for 22 days, did not inhibit the growth of control siRNA or TLR9 siRNA MDA-MB-231 breast cancer cells." (PMID 24273604, 2013). "More important, CpG ODN, and even non-CpG ODN, can activate TLR9 expressed in breast cancer cell lines and prostate cancer cell lines, resulting in increased cellular invasion." (PMID 23251529, 2012). "In conclusion, non-CIC breast cancer cells feature oncolytic adenovirus recognition by TLR9 and TLR2 and intact TLR trafficking, whereas CIC have defects in trafficking of TLR9 and co-factor MyD88 and lack of TLR2." (PMID 21079774, 2010).
breast cancer (continued). "For example, TLR2 signaling has been shown to promote lung cancer cell growth and resistant of apoptosis; TLR3 can directly trigger apoptosis in human cancer cells, such as breast cancer cells, TLR2 and TLR9 can promote invasiveness and metastasis through metalloproteases and integrins." (PMID 20618976, 2010). "Also, adenovirus staining colocalized with TLR9 in endosomes and with TLR2 on the cell surface indicating that in this breast cancer cell type TLR9 and TLR2 are active in virus recognition." (PMID 21079774, 2010). "Moreover, TLR3 and TLR9 exhibited varying expression levels in estrogen receptors (ER-)/progesterone receptors (PR-) negative breast cancer when contrasted with control tissues." (PMID 41550509, 2026). "There are, however, no previous reports on HPV’s effects on TLR9 expression in breast cancer." (PMID 39644451, 2024). "However, MMP8 was shown not to be involved in the tumor-promoting effects of TLR9 and relaxin that induced the activity of many MMPs in breast cancer cells thereby increasing cell invasiveness." (PMID 31514474, 2019). "Previous studies have also demonstrated that TLR9 expression may regulate cancer cell invasion, even in the absence of ligands in breast cancer cells." (PMID 26087186, 2015). "Whether synthetic TLR9 agonists also induce the expression of inflammatory mediators in breast cancer cells, is not known." (PMID 25101078, 2014). "We previously demonstrated that TLR9 has an important role in TNBC and showed that, while low tumor TLR9 expression was associated with significantly shortened breast cancer-specific survival in patients with TNBC, TLR9 had no prognostic value in breast cancer patients with ER+ tumors." (PMID 24273604, 2013).
lung carcinoma (54 papers, 2005 to 2025). "We previously demonstrated that S1P is involved in the exacerbation of the TLR9-induced inflammatory pathway associated to lung cancer, as well as in cell proliferation through a SPHK II/S1PR3 nuclear-dependent intracellular mechanism." (PMID 37176007, 2023). "Conversely, TLR9 expression was linked to an angiogenic phenotype, cancer progression, and worse survival in carcinoma of the lung." (PMID 34573939, 2021). "For example, TLR9 signaling has been associated with an enhanced metastatic potential of lung cancer cells." (PMID 34573939, 2021). "The association of miR-574-3p with lung cancer, has been observed in several studies where an upregulation resulted from TLR9 signaling." (PMID 32647120, 2020). "For example, the TLR4 ligand (LPS) causes resistance to anticancer therapies of ovarian and lung cancers whereas activation of TLR9 by CpG DNA causes apoptosis of lung cancer cells." (PMID 28427199, 2017). "Several studies have investigated the association between pDCs and TLR9 expression in lung cancer." (PMID 37435086, 2023). "In lung cancer, TLR9 may be linked to metastatic properties, and TLR9 activation also stimulates prostate-cancer invasion." (PMID 31314777, 2019). "Our findings indicated that HuR could act as regulator in regulating TLR9 signaling associated biological effect in human lung cancer cells, which might be helpful for the understanding of the potential role of HuR in tumor biology." (PMID 24004462, 2013). "However, the underlying mechanism regulating the expression of TLR9 signaling-associated miRNAs in lung cancer cells remains largely unknown." (PMID 24004462, 2013). "Our findings indicated that HuR could act as regulator in regulating TLR9 signaling associated biological effect in human lung cancer cells through a positive feedback loop, which might be helpful for the understanding of the potential role of HuR in tumor biology." (PMID 24004462, 2013). "CPT modulates miR-574-5p expression via promoter methylation and targets protein tyrosine phosphatase receptor type U (PTPRU) to influence TLR9 signaling, thereby affecting apoptosis and improving lung cancer." (PMID 41154678, 2025). "Studies have found that TLR9 can promote the progression of lung cancer, and miR-7 can inhibit the growth and metastasis of lung cancer cells by regulating the PIK3R3/Akt pathway and inhibiting the TLR9 signaling pathway." (PMID 37627250, 2023). "It seems to be well-confirmed that TLR9 signalling increases the expression of miR-574 in human lung cancer cells." (PMID 38085380, 2023). "Another more in-depth study found that TLR9 can enhance the expression of human antigen R (HuR) in human lung cancer cells through the Akt pathway." (PMID 37627250, 2023). "In an animal model of lung cancer, ionizing radiation induced robust TLR9 expressing immune cells in peritumoral area." (PMID 37435086, 2023). "The authors used a single cell line (A549), but showed compelling evidence that treatment with a TLR9 agonist increases the radiosensitivity of lung cancer cells." (PMID 37112730, 2023). "miRNA array analysis showed that it was the most upregulated miRNA in human lung cancer cells under Toll-like receptor 9 (TLR9) signaling." (PMID 36671425, 2022). "NSCLC patients without metastasis have lower mitochondrial DNA (mtDNA) and lower TLR9 expression compared to those with metastasis; therefore, TLR9 and mtDNA can serve as potential biomarkers for lung cancer progression and metastasis." (PMID 36389785, 2022). "miR-7 is also shown to target phosphoinositide-3-kinase regulatory subunit 3 (PIK3R3) in lung cancer cells, and the down-regulation of the PIK3R3/Akt pathway attenuates the TLR9 signaling-induced growth and proliferation of lung cancer cells." (PMID 36555120, 2022).
lung carcinoma (continued). "TLR4 and TLR9 increase miRNA expression of miR-21 and miR26a, respectively, in a xenograft model or primary human lung cancer cells." (PMID 29190881, 2017). "CpG ODN is TLR9 activator with potential immune modulatory effects and sensitization of radiotherapy in lung cancer." (PMID 26842986, 2016). "A number of studies have shown that miR-7 also is involved in the signal transduction and regulatory processes of other membrane-bound proteins in lung cancer cells, such as the pattern-recognition molecules Toll-like receptor 9 (TLR9)." (PMID 26516313, 2015). "In lung cancer patients, accumulating evidence suggested that TLR9 signaling played a crucial role in anti-tumor immunity." (PMID 25788863, 2014). "In previous study, we reported down-regulation of intrinsic miR-7 was critical for TLR9 signaling enhanced progression of human lung cancer cells through altering the expression of PIK3R3." (PMID 24004462, 2013). "The expression of HuR in human lung cancer 95D cells treated with TLR9 agonist CpG Oligonucleotides (ODNs) was detected by Real-time PCR and Western blot assay." (PMID 24004462, 2013). "Our most recent study also showed that downregulation of intrinsic miR-7 was important for TLR9 signaling enhanced growth and metastatic potential of human lung cancer cells." (PMID 24004462, 2013). "Our previous study also showed that PI3KAkt pathway was critical for TLR9 signaling enhanced metastatic potential of lung cancer cells." (PMID 24004462, 2013). "One newly evidence also showed that upregulation of miRNA-574-5p was critical for TLR9 signaling enhanced tumor progression of human lung cancer." (PMID 24004462, 2013). "Here, we carefully evaluated the potential role of HuR in the expression of miR-7 on TLR9 signaling treated human lung cancer cells." (PMID 24004462, 2013). "Previous studies showed that TLR9 is expressed in human lung cancer A549 cells and human hepatoma HepG2 cells." (PMID 24161202, 2013). "In fact, we found that miR-7 was also an important player in TLR9 signaling in human lung cancer (unpublished data)." (PMID 23133627, 2012). "To address this issue, here we characterized the effect of miRNA-574-5p which was up-regulated under TLR9 signaling in human lung cancer cells." (PMID 23133627, 2012). "Here we characterized the potential role of miRNA-574-5p in enhanced tumor progression induced by TLR9 signaling in human lung cancer." (PMID 23133627, 2012). "We further showed that up-regulation of cyclin-dependent kinase 2 (CDK2) was critical for TLR9 signaling to stimulate the proliferation and cell cycle entry of human lung cancer cells." (PMID 23133627, 2012). "We found that miRNA-574-5p was pivotal for TLR9 signaling to enhance the tumor progression of human lung cancer cells." (PMID 23133627, 2012). "We first confirmed the enhanced tumor progression of human lung cancer induced by TLR9 signaling, and found that CpG ODNs treatment of 95D cells significantly enhanced their proliferation in vitro and tumor progression in vivo (p<0.05)." (PMID 23133627, 2012). "Our findings strongly demonstrated that TLR9 signaling effectively elevated the expression of miR-574-5p in human lung cancer cells." (PMID 23133627, 2012). "We confirmed that TLR9 signaling effectively elevated the expression of miR-574-5p in human lung cancer cells." (PMID 23133627, 2012). "In conclusion, here we extended previous study by demonstrating that miR-574-5p was pivotal for TLR9 signaling enhanced tumor progression via down-regulating Ches1 in human lung cancer." (PMID 23133627, 2012). "To further investigate the potential role of miR-574-5p in the effect of TLR9 signaling on human lung cancer patients, we detected the relationship between the expression of miR-574-5p and TLR9 in clinical NSCLC patients." (PMID 23133627, 2012).
lung carcinoma (continued). "We, therefore, examined effect of combining RT with a designer synthetic agonist of TLR9 on anti-tumoral immunity, primary tumor growth retardation and metastases in a murine model of lung cancer." (PMID 22666458, 2012). "Combining these data suggested that miR-574-5p conferred the effect of TLR9 signaling on tumor progression of human lung cancer cells." (PMID 23133627, 2012). "The expression levels of TLR9 and miR-574-5p were higher in lung cancer tissue compared with adjacent tissue of tumor from clinical lung cancer samples (p<0.05)." (PMID 23133627, 2012). "Here we extended our previous study by demonstrating that up-regulation of miR-574-5p conferred the enhanced tumor progression induced by TLR9 signaling in human lung cancer cells." (PMID 23133627, 2012). "We further showed that miR-574-5p was the mostly up-regulated miRNA in human lung cancer cells under TLR9 signaling by miRNA array analysis." (PMID 23133627, 2012). "Here we show that TLR9 is expressed in a selection of human lung cancer tissues and various tumor cell lines." (PMID 15631627, 2005). "We found high signal intensities for TLR9 transcripts in the cytoplasm of tumor cells in the majority of lung cancer specimens." (PMID 15631627, 2005). "We found high TLR9 signal intensities in the cytoplasm of tumor cells in the majority of lung cancer specimens as well as in all tested tumor cell lines." (PMID 15631627, 2005). "Finally, results from lung cancer studies suggest that combination of immune checkpoint inhibitors and TLR9 agonists lead to successful anti-lung cancer immune re-activation." (PMID 36798234, 2024). "Therefore, the anti-lung cancer activity of Intercedenside C is in line with the present findings, which demonstrate its high affinity to TLR9." (PMID 37233477, 2023). "TLR9 is highly expressed at the mRNA and protein levels in lung cancer." (PMID 36389785, 2022). "A mouse model of lung carcinoma showed that TLR9 activation in B cells promotes tumor regression." (PMID 36389785, 2022). "In this context, we hypothesized that SPG β-glucan can activate TLR-9 and M1 Mφs to initiate an effective immune response against lung cancer cells." (PMID 34202080, 2021). "The toll-like receptor (TLR) is one of the innate immunospecific receptors, and the TLR9 signals in both in vivo and in vitro experiments could promote the metastasis of human lung cancer cells." (PMID 31214487, 2019). "As such, activation of TLR4 or TLR9 enhanced growth and metastasis of lung cancer." (PMID 29568370, 2018). "Finally, high TLR9 expression was also observed in both primary lung cancer specimens and tumor cell lines, and activation of the TLR9 pathway resulted in the production of monocyte chemoattractant protein-1 (MCP-1) and the reduction of TNFα-induced apoptosis." (PMID 27733853, 2016). "TLR9 agonist could enhance the metastatic potential of human lung cancer 95D cells via CXCR4/SDF-1(chemokine receptor 4/chemokine ligand 12) pathway." (PMID 26087186, 2015). "Our data showed that TLR9 agonist CpG ODNs could induce the expression of HuR in human lung cancer cells." (PMID 24004462, 2013). "Importantly, in contrast to previous findings, we characterized that up-regulation of HuR was contributed to TLR9 signaling enhanced growth and metastatic potential of human lung cancer through altering the expression of miR-7." (PMID 24004462, 2013). "In addition, it should be noted that our previous data also showed the activity of miR-7 promoter also decreased in TLR9 signaling treated human lung cancer cells." (PMID 24004462, 2013). "However, the mechanism that downregulation of miR-7 in TLR9 signaling treated lung cancer cells remains to be investigated." (PMID 24004462, 2013). "Importantly, we further found that up-regulation of HuR was contributed to TLR9 signaling enhanced growth and metastatic potential of human lung cancer cells." (PMID 24004462, 2013).